NOTCH1 (notch receptor 1)
Diseases named in the same sentence as NOTCH1 in open-access papers (continued):
Sharing a sentence is not in itself a finding about the gene and the disease.
pancreatic cancer (continued). "Furthermore, over-expression of Notch-1 has been found led to the acquisition of EMT phenotype by up-regulation of mesenchymal cell markers, ZEB1, ZEB2, Snail2, and down-regulation of epithelial cell marker, E-cadherin, in pancreatic cancer cells." (PMID 29202800, 2017). "We next determined whether lack of Notch-1 activation is the reason for reduced growth of pancreatic cancer cells." (PMID 26673007, 2016). "Our earlier studies have shown that CDF could function as a potent anti-tumor agent against human pancreatic tumor in vitro and in vivo by regulating miRNAs, CSC phenotype and function, and multiple cellular signaling pathways such as NF-κB, Akt, COX-2, Notch-1, and EZH2." (PMID 23272057, 2012). "However, Notch1 has also been shown to regulate the expression and activation of MMP9 through NF-κB in pancreatic cancer cells, suggesting that the regulation of MMP9 expression and activity in endothelial cells by Notch may be mediated by NF-κB signaling." (PMID 21349159, 2011). "Also, the pancreatic cancer dataset in TCGA indicates that DLL4, NOTCH1, NOTCH2, and NOTCH3 levels do not affect survival." (PMID 35673567, 2022).
colorectal cancer (120 papers, 2011 to 2026). A primary or metastatic malignant neoplasm that affects the colon or rectum. "Previous studies have shown that 5‐FU‐resistant colorectal cancer cells exhibit elevated expression of stemness‐associated markers, including NOTCH1, CD44, ALDHA1, Oct4, SOX2, and Nanog." (PMID 41543046, 2026). "Increased expression of PSEN1 in colorectal cancer is associated with enhanced tumor development through heightened EGFR signaling via NOTCH1 processing and activation of the COX-2-PGE2 pathway." (PMID 39267750, 2024). "Another tumor-suppressing activity of miR-139-5p via NOTCH1 repression in colorectal cancer is the prevention of CD44+/CD133+-associated multidrug resistance." (PMID 35269391, 2022). "In colorectal cancer, increased NOTCH1 expression is associated with greater immune cell infiltration, tumor volume, and depth invasion." (PMID 36232418, 2022). "Forced expression of miR-139-5p causes the downregulation of NOTCH1 via direct binding to the 3′-UTR in colorectal cancer and inhibits the migration and invasion of tumor cells." (PMID 35269391, 2022). "We investigated four single nucleotide polymorphisms, each in genes encoding NOTCH1-4 receptors for their role in susceptibility to breast and colorectal cancers in Saudi population." (PMID 34257585, 2021). "The study underlined the potential role of Notch1 activation as an essential initial event triggering colorectal cancer." (PMID 32630477, 2020). "In conclusion, miR-139-5p downregulated NOTCH1 signaling to reverse CD44+/CD133+-associated MDR in colorectal cancer cells." (PMID 27738333, 2016). "Furthermore, other scholars have demonstrated a close association between the Notch1 signaling pathway and colorectal cancer." (PMID 40357397, 2025). "Since UC patients with long-lasting colonic inflammation have a higher risk of developing IBD-associated colorectal carcinoma, we hypothesize that downregulation of Notch-1 in these patients may potentially be involved in carcinogenesis." (PMID 38368394, 2024). "Additionally, enhanced Notch-1 signaling in colorectal cancer is simultaneously linked to the ability of Wnt/β-catenin to activate Notch-1 ligands, which appear to be critical for the growth of colorectal adenomas." (PMID 30323897, 2018). "Although there was growing evidence supporting the hypothesis that Notch1 was one of the few candidate genes linked with colorectal cancer (CRC) susceptibility, the precise level of Notch1 protein expression in benign and malignant colorectal diseases was still unknown." (PMID 24312514, 2013). "In fact, Notch signaling exhibits context‐dependent roles, with circFBXW7 suppressing NOTCH 1 in T‐ALL (tumor suppressor) versus circ‐NSD2 activating JAG1/NOTCH 1 in colorectal cancer (oncogene)." (PMID 40761890, 2025). "In one study, overexpression of the Notch1 intracellular domain (NICD1) in HCT-116 colorectal cancer cells—cells with naturally low NICD1 expression—led to enhanced nuclear translocation of β-catenin." (PMID 40869407, 2025). "The findings supported our selection of Notch1 SNP (rs3124591), which has been commonly studied in solid tumors, including breast and colorectal cancer." (PMID 41027955, 2025). "For example, DLL4 expressed by endothelial cells was shown to activate Notch signaling via Notch3 in T cell acute lymphatic leukemia and via Notch1 in colorectal cancer." (PMID 39951484, 2025).
colorectal cancer (continued). "Notch1 and CD10 expressions in colorectal carcinoma are associated with the progression of colorectal carcinoma (CRC) and partial response to treatment." (PMID 40060224, 2025). "This retrospective study included 100 cases of colorectal carcinoma that were immunohistochemically stained using Notch1 and CD10 antibodies." (PMID 40060224, 2025). "Immunohistochemistry studies reveal elevated Notch1 and Jagged1 expression in colorectal carcinoma and adenoma compared to adjacent carcinoma and normal tissues." (PMID 38844562, 2024). "In this cohort, data supported the antagonistic roles of NOTCH1 and NOTCH2 in phenotypes of colorectal cancer cells, where NOTCH1 acted as an oncogenic enhancer whereas NOTCH2 played a tumor suppressor role." (PMID 37860822, 2023). "The effect of JAG1 and NOTCH1 on pluripotency in colorectal cancer cells was observed in vitro where constitutive activation of Notch in colon tumor cell lines resulted in increased expression of EMT and stemness associated proteins." (PMID 37860822, 2023). "The latest study related to colorectal cancer published in 2023 showed that METTL3 influenced the proliferation, migration, and invasion of colorectal cancer cells through regulating Notch1 and Hsa_circ_0000390." (PMID 36970605, 2023). "Increased levels of RP11-59H7.3, a long non-coding RNA that is aberrantly expressed and correlates with poor prognosis of colorectal cancer, compete with NOTCH1 for miR-139 binding, thereby enhancing NOTCH1 oncogenic functions." (PMID 35269391, 2022). "The E3-ubiquitin ligase FBXW7 targets multiple substrates such as C-JUN, C-MYC, and NOTCH1; it works as a tumor suppressor for colorectal cancer by inhibiting Notch signal." (PMID 36147468, 2022). "In colorectal cancer, LAMA5 overexpression is associated with hepatic metastasis, angiogenesis, and NOTCH1 pathway inhibition." (PMID 36232418, 2022). "NOTCH1 expression is associated with poor survival as well as advanced grade or TNM stage in hepatocellular carcinoma (HCC) and colorectal cancer." (PMID 33801954, 2021). "In the present study, we evaluated for the first time the association of NOTCH1, rs3124591; NOTCH2, rs11249433; NOTCH3, rs1043994, and NOTCH4, rs3830041 SNPs with the susceptibility of breast and colorectal cancers in Saudi population." (PMID 34257585, 2021). "Recently, it has been shown that Notch 1 mediates the resistance effects of regorafenib in colorectal cancer cells." (PMID 33916610, 2021). "We examined the genotypes of four germline SNPs residing in NOTCH1 - rs3124591, NOTCH2 - rs11249433, NOTCH3 - rs1043994, and NOTCH4 - rs3830041 to determine their association with breast and colorectal cancer risk in Saudi Arabian patients." (PMID 34257585, 2021). "One study discovered that FAM83D knockdown regulates the biological behavior of colorectal cancer by inhibiting the FBXW7/Notch-1 signaling pathway." (PMID 34869310, 2021). "In colorectal cancer, when the tumor suppressor gene Aes is knocked out NOTCH1 becomes activated and stimulates ABL1 activity." (PMID 34022881, 2021). "Genistein prevents activation of Notch1 and its downstream targets and thus inhibits growth and differentiation in colorectal cancer." (PMID 34289845, 2021). "POFUT1 increased the activity of Notch1 signaling pathway and promoted the progression of colorectal cancer." (PMID 34221996, 2021). "In research on colorectal cancer cells resistant to Regorafenib, a high level of Notch-1 expression and transcription factors like HEY1 and HES1 has been observed." (PMID 33585000, 2020). "Previous studies have implicated miR-139-5p in the regulation of apoptosis, cell proliferation, suppression of tumor invasion, and cell migration by regulating NOTCH1 in colorectal cancer." (PMID 32507766, 2020).
colorectal cancer (continued). "Invasiveness of those colorectal cancer cells resistant to Regorafenib reduced the following Notch-1 knockdown." (PMID 33585000, 2020). "It was reported that miR-139-5p made colorectal cancer cells sensitive to 5-FU by suppressing NOTCH-1 expression." (PMID 32109290, 2020). "In colorectal cancer, Notch1 signalling leads to highly penetrant metastasis through control of inflammatory chemokine expression." (PMID 33168804, 2020). "Our results revealed a unique pathway for RP11-59H7.3/ NOTCH1/miR-139-5p regulation in colorectal cancer, suggesting that RP11-59H7.3 is a new biomarker for prognosis." (PMID 32507766, 2020). "More importantly, EGCG inhibited Notch1 and cleaved-Notch1 in 5-fluorouracil-resistant colorectal cancer cells." (PMID 32290543, 2020). "FAM83H-AS1, Notch1 and Hes1 were significantly increased in colorectal cancer samples and cell lines." (PMID 32839509, 2020). "The research draws out the crosstalk between miR-21 and the Notch1/PTEN pathway in Human Colorectal Cancer." (PMID 33151961, 2020). "In general, these findings indicated that RP11-59H7.3 triggers tumor-enhancing functions in colorectal cancer cells to some extent, and this is through miR-139-5p sponging and NOTCH1 regulation." (PMID 32507766, 2020). "Molecules in the Notch signaling pathways, including HES1, Notch-1, and Jagged-1, are highly expressed in colorectal cancer stem cells." (PMID 31198409, 2019). "Functional studies have demonstrated proliferative potential of FAM83H‐AS1 through MET/EGFR signaling in lung adenocarcinoma and NOTCH1 signaling pathway in colorectal cancer." (PMID 30959550, 2019). "Previous studies showed differential expression profiling of Notch1 and Notch2 in colorectal carcinoma specimens, which revealed up-regulation of Notch1 and down-regulation of Notch2 with significant relations to tumor differentiation status." (PMID 30988066, 2019). "Notch-1, Jagged-1 and Jagged-2 (two of the 5 Notch ligands), and its target gene Hes-1 are expressed in human primary adenocarcinomas and colorectal cancer cell lines." (PMID 30323897, 2018). "Crosstalk between Notch1 and Nuclear factor-κB (NFκB- p65) leads to activation of transcription factors involved in prosurvival signaling of cancer cells and contributes to colorectal cancer (CRC) cell proliferation and tumorigenesis." (PMID 30038258, 2018). "CD44+/CD133+-associated multidrug resistance is reversed by miR-139-5p, with a reduction in Notch1 in colorectal carcinoma cells." (PMID 30470250, 2018). "Genes of Notch signaling pathway such as Notch1, Notch2, HES1, DLL1, and JAG1 have been reported to be associated with the pathological tumor characteristics and degree of differentiation in colorectal cancer." (PMID 29100272, 2017). "Aberrant NOTCH1 signalling is critically involved in multiple models of colorectal cancer (CRC) and a prominent role of NOTCH1 activity during inflammation has emerged." (PMID 26864323, 2016). "In colorectal carcinoma cells, NOTCH1-deppendent activation of cell cycle and proliferation were mediated by repression of cyclin-dependent kinase inhibitor p27." (PMID 27938406, 2016). "Genetic and epigenetic alterations drive the initiation and progression of the adenoma–carcinoma sequence in colorectal cancer and aberrant activation of the Notch1 signaling is one of the identified pathway." (PMID 26650241, 2015). "FBXW7 encodes the substrate recognition component of a ubiquitin ligase that degrades targets such as Notch1, c-Jun, c-Myc and cyclin E. FBXW7 mutations occur in several tumour types, including colorectal cancers." (PMID 23676439, 2014).
colorectal cancer (continued). "Colorectal cancer patients with high expression levels of Notch1 showed lower overall survival (OS) and disease-free survival (DFS) rates than those patients with low Notch1 expression." (PMID 24312514, 2013). "Correlation between Notch1 expression and clinicopathological features in patients with colorectal cancer." (PMID 24312514, 2013). "Overall, colorectal cancer tissues exhibited dramatically higher levels of Notch1 protein expression compared with benign tissues (P<0.001)." (PMID 24312514, 2013). "Though Notch1 had been shown to be activated in colorectal cancer, its expression in benign colorectal patients was still uncertain." (PMID 24312514, 2013). "Cytoplasmic Notch1 was expressed in 7.7% of patients with ulcerative colitis, 14.7% of patients with colorectal adenoma and 58.0% of patients with colorectal cancer, respectively." (PMID 24312514, 2013). "We have recently reported that the putative intestinal stem cell marker musashi-1 (Msi-1) regulates Notch-1 in colorectal cancer." (PMID 21929751, 2011). "Here for the first time, we report that DCAMKL-1 regulates Notch-1 via a miR-144 dependent mechanism in colorectal cancer." (PMID 21929751, 2011). "In addition, quercetin can regulate Th cell responses, indirectly affect the Notch signaling pathway by inhibiting the NLRP3 inflammasome, and enhance colorectal cancer radiosensitivity via Notch1 pathway blockade." (PMID 41602823, 2026). "In colorectal cancer, the Notch1 signaling pathway plays an important role in the EMT process." (PMID 40630953, 2025). "CD10 and Notch1 may have roles in colorectal carcinoma progression via induction of tumor invasion, metastasis and impairment of tumor response to therapy." (PMID 40060224, 2025). "RT-PCR analysis indicates high Notch1 expression in colorectal carcinoma cell lines." (PMID 38844562, 2024). "In colorectal carcinoma, the loss of ITCH expression is associated with carcinogenesis, and ITCH might be involved in the Notch-1 pathway during colorectal carcinoma progression." (PMID 37760946, 2023). "However, colorectal cancer patients with co-morbid type 2 diabetes have abnormal cellular proliferation, which was correlated with increased Notch1/HES1 signaling and curbed by metformin treatment." (PMID 36672573, 2022). "Similarly, in colorectal cancer, Notch1 signaling retained the capabilities of suppressing the expression of Wnt target genes, even when B-Catenin destruction by APC complex was disabled." (PMID 33968932, 2021). "ADAM17 could regulate the chemical sensitivity of colorectal cancer stem cells by activating the Notch1 signaling pathway." (PMID 33535178, 2021). "In colorectal cancer primary samples, miR-34 was weakly expressed and inversely correlated with metastasis, whereas miR-34 overexpression suppressed cell invasiveness and migration by targeting Notch1 and JAG1." (PMID 34680255, 2021). "Consistently, restoring the activity of the enzymatic counterpart of JMJD3 PRC2 through STRAP silencing counteracted transcriptional upregulation of Notch1 and smothered stem-like features of colorectal cancer cells, resulting in tumor sensitization to oxaliplatin in vivo and in vitro." (PMID 34680255, 2021). "Recently, missense activating mutations in the Notch 1 and Notch 2 receptors have been identified in colorectal cancer; however, the functional relevance was not reported." (PMID 32575680, 2020). "Additionally, the results herein further revealed that RP11-59H7.3 performs tumor-enhancing roles through miR-139-5p sponging and regulation of NOTCH1 expression in colorectal cancer." (PMID 32507766, 2020).